PDCD5 (programmed cell death 5)
Diseases named in the same sentence as PDCD5 in open-access papers (continued):
Sharing a sentence is not in itself a finding about the gene and the disease.
dilated cardiomyopathy (2 papers, 2012 to 2020). Cardiomyopathy which is characterized by dilation and contractile dysfunction of the left and right ventricles. "High over-expression of human PDCD5 leads to dilated cardiomyopathy and sudden death." (PMID 22253891, 2012). "Taken together, high PDCD5 over-expressing line developed dilated cardiomyopathy and heart failure." (PMID 22253891, 2012). "Given that PDCD5 is upregulated in hypertrophied heart and high over-expressing line develops dilated cardiomyopathy and heart failure, we hypothesized that low over-expressing line may be more susceptible to Ang II-induced cardiac hypertrophy." (PMID 22253891, 2012). "Indeed, high PDCD5 over-expression (10 fold) led to autophagy activation, dilated cardiomyopathy and sudden death." (PMID 22253891, 2012). "Furthermore, in transgenic (Tg) mouse hearts that overexpress programmed cell death 5 (PDCD5) and have dilated cardiomyopathy, autophagy activity is increased." (PMID 32195266, 2020).
multiple sclerosis (2 papers, 2015 to 2025). A progressive autoimmune disorder affecting the central nervous system resulting in demyelination. "In addition, upregulated PDCD5 expression has been observed in peripheral mononuclear cells from patients with multiple sclerosis and Hashimoto's Thyroiditis." (PMID 40111008, 2025).
osteosarcoma (2 papers, 2015 to 2016). A usually aggressive malignant bone-forming mesenchymal neoplasm, predominantly affecting adolescents and young adults. "The studies have confirmed that PDCD5 also suppresses tumorigenesis by inhibiting the Ras/Raf/MEK/ERK signaling pathway in the human osteosarcoma cell line MG-63 and adenovirus carrying PDCD5 gene exerts potent antitumor efficacy on common human leukemic cell lines." (PMID 27398268, 2016).
acute lymphoblastic leukemia (1 paper, 2015). Leukemia with an acute onset, characterized by the presence of lymphoblasts in the bone marrow and the peripheral blood. "Since our approach so far was to investigate the loss of function of PDCD5 in cell death, we finally generated two acute lymphoblastic leukemia (ALL) cell lines (PreB697 and CEM) stably overexpressing 3xFlag-PDCD5." (PMID 26062895, 2015).
Alzheimer disease (1 paper, 2023). A progressive, neurodegenerative disease characterized by loss of function and death of nerve cells in several areas of the brain leading to loss of cognitive function such as memory and language. "Elevated levels of PDCD5, ENO1, CHI3L1, PP3R1 and SCRN1 have been observed in CSF from individuals with Alzheimer disease." (PMID 36721240, 2023).
autoimmune disease (1 paper, 2016). A disorder resulting from loss of function or tissue destruction of an organ or multiple organs, arising from humoral or cellular immune responses of the individual to their own tissue constituents. "Programmed cell death 5 (PDCD5) was first identified as an apoptosis-promoting protein and involved in some autoimmune diseases and inflammatory processes." (PMID 27846830, 2016).
brain ischemia (1 paper, 2023). Diminished or absent blood supply to the brain caused by obstruction (thrombosis or embolism) of an artery resulting in neurologic damage. "The previous reports have shown that the inhibition of Pdcd5 expression in a brain ischemia/reperfusion model improves neurological deficits and cerebral blood flow, reduces the infarct volume, and protects the BBB via suppressing the process of neuronal apoptosis and autophagy." (PMID 36875640, 2023).
cardiac hypertrophy (1 paper, 2012). "It will be interesting to further examine the function and decipher the precise molecular mechanisms of PDCD5 in cardiac hypertrophy and heart failure using loss-of-function method." (PMID 22253891, 2012). "Transgenic mice with low over-expression of PDCD5 are more susceptible to angiotensin II (Ang II)-induced cardiac hypertrophy." (PMID 22253891, 2012). "Low over-expression of human PDCD5 is more susceptible to Ang II-induced cardiac hypertrophy." (PMID 22253891, 2012). "In conclusion, PDCD5 is upregulated in the development of cardiac hypertrophy." (PMID 22253891, 2012).
colorectal cancer (1 paper, 2017). A primary or metastatic malignant neoplasm that affects the colon or rectum. "We co-transfected PDCD5 and various phosphatases into the human colorectal carcinoma cell line HCT116, and analyzed the associations of PDCD5 with these phosphatases by immunoprecipitation using antibody against Myc." (PMID 28051100, 2017).
endometrial carcinoma (1 paper, 2016). A malignant tumor arising from the epithelium that lines the cavity of the uterine body. "It is clear that PDCD5 protein expression was lower in middle and low differentiated endometrial carcinoma compared with control endometrium and high differentiated endometrial carcinoma." (PMID 27398268, 2016). "Furthermore, PDCD5 protein level was significantly lower in endometrial carcinoma samples than that in control endometrium." (PMID 27398268, 2016). "Therefore, PDCD5 may play a key role in the pathogenesis of endometrial cancer and may be a novel target for diagnosis and treatment of endometrial cancer." (PMID 27398268, 2016). "However, the expression of PDCD5 and its clinical significance in endometrial cancer have not been fully elucidated." (PMID 27398268, 2016). "However, the expression and clinical significance of PDCD5 in endometrial cancer have not been fully elucidated." (PMID 27398268, 2016). "However, it remains not very clear about PDCD5 expression in endometrial cancer." (PMID 27398268, 2016).
endometrioid endometrial carcinoma (1 paper, 2016). "In the current study, we found that PDCD5 protein was reduced in endometrioid endometrial carcinoma tissues and its levels were associated with the degree of tumor differentiation." (PMID 27398268, 2016). "Here, we evaluated the expression of PDCD5 in endometrioid endometrial carcinoma and control endometrium by qRT-PCR, western blot and immunohistochemistry, and analyzed the associations of PDCD5 expression with clinicopathological parameters of patients." (PMID 27398268, 2016). "Furthermore, we analyzed the associations of PDCD5 expression with clinical and pathological characteristics of patients with endometrioid endometrial carcinoma." (PMID 27398268, 2016). "The results from IHC revealed PDCD5 protein was mainly located in the cytoplasm of the control endometrial glandular cells or endometrioid endometrial carcinoma cells, and there was also a low level of PDCD5 expression in the nuclei of these cells." (PMID 27398268, 2016). "To verify the results of western blot, we next determine the levels of PDCD5 protein expression in 51 endometrioid endometrial carcinoma tissues and 53 control endometrium using IHC staining." (PMID 27398268, 2016). "The levels of PDCD5 protein were downregulated in middle-low differentiation of endometrioid endometrial carcinoma samples compared with high differentiation endometrioid endometrial carcinoma samples." (PMID 27398268, 2016). "In order to study the roles of PDCD5 in endometrioid endometrial carcinoma, we firstly detected PDCD5 mRNA expression in 16 freshly frozen endometrioid endometrial carcinoma tissues and 17 control endometrium using qRT-PCR." (PMID 27398268, 2016). "To further explore the expression status of PDCD5 in endometrioid endometrial carcinoma, we detected the levels of PDCD5 protein in 16 freshly frozen endometrioid endometrial carcinoma tissues and 17 control endometrium using western blot." (PMID 27398268, 2016). "The data showed that the expression of PDCD5 protein in endometrioid endometrial carcinoma tissues was significantly lower than that in control endometrium, which was inconsistent with the results of qRT-PCR (P < 0.001)." (PMID 27398268, 2016). "In the present study, we demonstrated that PDCD5 protein expression was decreased in endometrioid endometrial carcinoma tissues compared with control endometrium by western blot." (PMID 27398268, 2016). "In order to explore the clinical significance of PDCD5 expression in endometrioid endometrial carcinoma, we analyzed the relationships between PDCD5 expression levels and the clinicopathological parameters." (PMID 27398268, 2016). "In addition, we detected the expression of PDCD5 in control endometrial glandular epithelial cells and endometrioid endometrial carcinoma-derived cell line KLE by immunocytochemistry." (PMID 27398268, 2016). "In order to further confirm the results, we isolated and identified control endometrial glandular cells and stromal cells, and then detected the PDCD5 expression in control endometrial glandular epithelial cells and stromal cells, as well as endometrioid endometrial carcinoma cell line KLE." (PMID 27398268, 2016). "However, the detailed regulation mechanism of decreased PDCD5 expression in endometrioid endometrial carcinoma requires further investigation." (PMID 27398268, 2016). "Therefore, we further analyzed the differences in PDCD5 protein expression between control endometium and high differentiation or middle-low differentiation of endometrioid endometrial carcinoma samples." (PMID 27398268, 2016). "We speculate that the differences in PDCD5 mRNA and protein levels may be because the expression of PDCD5 could have post-transcriptional regulation in endometrioid endometrial carcinoma." (PMID 27398268, 2016). "The results suggested that PDCD5 expression might have an important role in the development and progression of endometrioid endometrial carcinoma and might contribute to the improvement of prognosis." (PMID 27398268, 2016).
endometrioid endometrial carcinoma (continued). "The results showed that PDCD5 protein expression was decreased in endometrioid endometrial carcinoma tissues and correlated with the degree of tumor differentiation, suggesting that PDCD5 could participate in the development and progression of endometrioid endometrial carcinoma." (PMID 27398268, 2016). "However, unlike other tumors, PDCD5 mRNA levels had no apparent change between endometrioid endometrial carcinoma tissues and control endometrium." (PMID 27398268, 2016). "In this study, we found that PDCD5 protein levels were not related to age, myometrial invasion, FIGO stage, estrogen receptor and progestin receptor of patients with endometrioid endometrial carcinoma." (PMID 27398268, 2016).
fibrosis (1 paper, 2021). the formation of excess fibrous connective tissue in an organ or tissue in a reparative or reactive process. "Since PDCD5 expression was increased in the lungs of patients with IPF and in the lungs of mice with fibrosis, we examined whether CK2-mediated phosphorylation of PDCD5 at Ser-119 is required for PDCD5 stabilization and nuclear translocation in response to TGF-β1." (PMID 34011956, 2021).
hypothyroidism (1 paper, 2018). Abnormally low levels of thyroid hormone. "The increased PDCD5 expression in patients with hypothyroidism as well may reflect the enhanced apoptotic processes in these patients." (PMID 29527211, 2018).
lung adenocarcinoma (1 paper, 2022). A carcinoma that arises from the lung and is characterized by the presence of malignant glandular epithelial cells. "Besides, PDCD5 expression has been observed to be significantly reduced in highly differentiated lung adenocarcinoma, whereas the re-expression of PDCD5 exerts anti-tumorigenic effects by curbing malignant cell proliferation." (PMID 36266728, 2022).
lung disease (1 paper, 2021). "To investigate the pathological relevance of PDCD5 in lung disease, we examined PDCD5 expression in lung tissues from patients with IPF using immunohistochemistry (IHC)." (PMID 34011956, 2021).
nasopharyngeal carcinoma (1 paper, 2022). A carcinoma arising from the nasopharyngeal epithelium. "Survival analysis showed that the expression of high levels of miRNA-19a-3p or low levels of PDCD5 had a poorer prognosis in patients with nasopharyngeal carcinoma." (PMID 36591507, 2022).
osteoporosis (1 paper, 2015). A condition of reduced bone mass, with decreased cortical thickness and a decrease in the number and size of the trabeculae of cancellous bone (but normal chemical composition), resulting in increased fracture incidence. "Above all, our findings suggested a novel mechanism for osteoporosis, which is attenuation of monocyte apoptosis, as supported by the 4 apoptosis genes’ (DAXX, PLK3, VDAC1 and PDCD5) down-regulation in the low BMD subjects." (PMID 25659073, 2015).
skin cancer (1 paper, 2022). "The anti-tumor properties of PDCD5 have been reported in mice with skin cancer by contributing to apoptosis." (PMID 36266728, 2022).
triple-negative breast carcinoma (1 paper, 2023). An invasive breast carcinoma which is negative for expression of estrogen receptor (ER), progesterone receptor (PR), and human epidermal growth factor receptor 2 (HER2). "We found that the expression of genes related to apoptosis and DNA degradation, such as Cad, PDCD5, Dnase2 and Bax, increased after nsPEF ablation of triple-negative breast cancer in mice." (PMID 37046739, 2023).
tumor (18 papers, 2012 to 2025). "However, we found that the expression of PDCD5 was significantly associated with the degree of tumor differentiation (P < 0.05)." (PMID 27398268, 2016). "However, the expression of PDCD5 was significantly associated with the degree of tumor differentiation." (PMID 27398268, 2016). "PDCD5 has been found to be phosphorylated at Ser119 and quickly translocated into the nucleus in tumor cells in response to genotoxic stress." (PMID 40111008, 2025). "- miR-766 can inhibit apoptosis and induce invasion, migration, and proliferation of SCL-1 and A431 cells by decreasing the expression level of PDCD5.- Inhibition of miR-766 decreases tumor growth in mice." (PMID 37205191, 2023). "Collectively, our experimental data demonstrated that PDCD5 harbored tumor-suppressive property by inhibiting the proliferation of RCC cells and enhancing the immune functions of T cells via the HDAC3/miR-195-5p/SGK1 axis." (PMID 36266728, 2022). "PDCD5 is a member of the family of programmed cell death proteins, which are often involved in tumor growth and cell apoptosis." (PMID 32248621, 2020). "Among the identified proteins, PDCD5, a tumour suppressor that was recently found to act as a pro-apoptotic factor, was particularly interesting and thus selected for this study." (PMID 26077467, 2015). "PDCD5 overexpression can attenuate tumor invasion, EMT and IGF-1 protein induced by TGF-β treatment." (PMID 25436001, 2015). "PDCD5 overexpression can attenuate tumor invasion, EMT and the level of IGF-1 protein induced by TGF-β treatment." (PMID 25436001, 2015). "Programmed death gene 5 (PDCD5) has an effect of promoting tumor cell apoptosis and inhibiting tumor cell proliferation." (PMID 25311560, 2014). "PDCD5 is initially identified as a tumor suppressor, which inhibits cell growth in a variety of cancer cells by inducing apoptosis." (PMID 22253891, 2012). "Additionally, PDCD5 has been shown to facilitate the degradation of histone deacetylase HDAC3 in tumor cells and endothelial cells." (PMID 40111008, 2025). "Future studies using Pdcd5 conditional knockout mice crossed with other mice tumor models will be necessary to identify if the embryonic lethality of Pdcd5 homozygous deletion can be overcome and to clarify the potential role of Pdcd5 as a tumor suppressor in vivo." (PMID 28542142, 2017). "Recent studies showed that PDCD5 might be a new tumor suppressor gene and involved in tumor development and progression." (PMID 27398268, 2016). "The decreased PDCD5 expression was correlated with the tumor differentiation degree." (PMID 27398268, 2016). "There are few studies on the correlation between PDCD5 and tumor invasion." (PMID 25436001, 2015). "It was demonstrated that the transfection of PDCD5 into HepG2 cells could change the biological behaviors of tumors, such as the cellular proliferation, cell cycle progression, cisplatin sensitivity, tumor invasion and EMT." (PMID 25436001, 2015).
tumor (continued). "Genes CBX3, RCC1, TMOD3, and NOA1 (Cluster A) and TOP1, PDCD5, and THRAP3 (Cluster B) were upregulated for both datasets in PCa tissue vs. normal gland or normal adjacent to tumor tissue." (PMID 32640729, 2020). "This means that PDCD5 has an inhibitory effect on EMT in HCC cells, and provided a novel anti-tumor strategy for treating HCC." (PMID 25436001, 2015). "Programmed cell death 5 (PDCD5) was initially cloned from apoptotic TF-1 cells and currently known as a tumor suppressor candidate." (PMID 22253891, 2012). "Moreover, we found a significantly positive correlation between the expression levels of PDCD5 and LNPPS in tumour tissues from 30 BC patients." (PMID 36578176, 2023). "Pdcd5 is a tumor-suppressor protein that is an interaction partner, but not a folding substrate, of CCT and can bind to CCT to specifically inhibit β-tubulin folding, potentially by sterically hindering β-tubulin binding to CCT." (PMID 30506376, 2019). "Programmed cell death protein 5 (PDCD5), also designated TFAR19 (TF-1 cell apoptosis related gene-19), could enhance apoptosis in different tumor cells (e.g., HeLa, TF-1, MCG-803, and MCF-7)." (PMID 24509810, 2014).